ANXA10 (annexin A10)
Synonyms: ANX14
Tractability: Antibody: its Gene Ontology location is reachable by antibodies, with medium confidence. PROTAC: ubiquitination databases record sites on it.
Gene: Protein-coding gene on chromosome 4 (168,092,537 to 168,187,736, forward strand). Ensembl gene ENSG00000109511.
Subcellular location (Human Protein Atlas): Nucleoli; Nucleoplasm; Vesicles
Gene Ontology:
Molecular function: protein binding; calcium ion binding; calcium-dependent phospholipid binding; phosphatidylserine binding
Cellular component: nucleus; plasma membrane; vesicle membrane
Genetic constraint (gnomAD): Loss-of-function variants: 24 observed, 29.45 expected, observed/expected ratio (o/e) 0.82, 90% interval 0.59 to 1.15. The upper end of that interval is the gene's LOEUF score, 1.15, which puts it in group 5 of 6, group 1 being the genes least tolerant of losing a copy. Missense variants: 259 observed, 261.78 expected, observed/expected ratio (o/e) 0.99, 90% interval 0.89 to 1.1. Synonymous variants: 87 observed, 85.92 expected, observed/expected ratio (o/e) 1.01, 90% interval 0.85 to 1.21.
Homologues: Orthologues: chimpanzee ANXA10 (98% identical), macaque ANXA10 (97% identical), dog ANXA10 (91% identical), guinea pig ANXA10 (91% identical), mouse Anxa10 (89% identical), pig ANXA10 (88% identical), rat Anxa10 (86% identical), tropical clawed frog anxa10 (77% identical), Drosophila melanogaster AnxB9 (39% identical), Drosophila melanogaster AnxB11 (38% identical), zebrafish anxa14 (28% identical). Paralogues in human: ANXA4 (44% identical), ANXA3 (44% identical), ANXA11 (42% identical), ANXA6 (42% identical), ANXA1 (39% identical), ANXA8L1 (39% identical), ANXA2 (38% identical), ANXA8 (38% identical), ANXA7 (38% identical), ANXA5 (37% identical), ANXA13 (34% identical), ANXA9 (31% identical).
Diseases named in the same sentence as ANXA10 in open-access papers:
ANXA10 is named in the same sentence as 60 diseases in open-access papers, as found by Europe PMC text mining. Sharing a sentence is not in itself a finding about the gene and the disease. The quoted sentences say what the papers report.
gastric cancer (18 papers, 2011 to 2025). A primary or metastatic malignant neoplasm involving the stomach. "Five proteins were associated with the risk of stomach cancer including ANXA10 and TFF1 [1.75 (1.51–2.02) and 1.90 (1.58–2.28)]." (PMID 38750076, 2024). "Collectively, our results of GDSC data analysis suggest that the molecular interplay between ARK family genes and ANXA10/ZNF162 activity play key role in the mechanisms underlying acquired resistance/sensitivity to gastric cancer drugs." (PMID 35974335, 2022). "Loss of ANXA10 expression is frequent in early gastric cancer, and constitutes an independent biomarker of poor prognosis." (PMID 36247003, 2022). "ANXA10 is specifically expressed in gastric epithelial cells and is frequently downregulated in human gastric cancer, making this an appropriate driver for gastric-specific genetic manipulation." (PMID 40673273, 2025). "ANXA10 is related to poor prognosis of patients with early gastric cancer, small bowel adenocarcinoma, and lung adenocarcinoma." (PMID 37229243, 2023). "For gastric cancer, findings related to the prognostic values of annexin A10 have been inconsistent." (PMID 35227227, 2022). "Decreased ANXA10 has been correlated with increased invasion in a colorectal cancer cell line and with the increased proliferation and migration in a gastric cancer cell line." (PMID 31052599, 2019). "The association of ANXA9 with pathogenic prognosis in colorectal cancer contrasts with a proposed tumor suppressor role for ANXA10 in gastric cancer." (PMID 30744186, 2019). "This is in agreement with earlier cell line studies, revealing that decreased ANXA10 was correlated with increased invasion in a colorectal cancer cell line and with increased proliferation and migration in a gastric cancer cell line." (PMID 21979422, 2011). "It has also been suggested that ANXA10 may constitute a predictive biomarker of chemotherapy response in gastric cancer." (PMID 36247003, 2022). "Notably, the Anxa10-CreERT2 mice with Cdh1 and Smad4 deletion, simultaneously with Kras activation, developed poorly differentiated tumors with diffuse-type gastric cancer morphology, which was histologically characterized by signet ring cells." (PMID 36369466, 2022). "Despite various investigations, this is the first report of ANXA10 in early-stage gastric cancer." (PMID 33177783, 2020). "Decreased ANXA10 has been correlated with increased invasion in a colorectal cancer cell line and with increased proliferation and migration in a gastric cancer cell line." (PMID 21979422, 2011). "Notably, the annexin A10 (Anxa10) gene, which is specifically expressed in the stomach epithelium, was selected as the driver for CreERT2 expression, thereby allowing highly precise modeling of human gastric cancer subtypes." (PMID 40673273, 2025). "In addition, a recent study demonstrated that the stomach-specific and inducible Cre recombinase mouse line Anxa10-CreERT2 allows the modeling of different known subtypes of gastric cancer, although in this study only the evaluation of CIN and GS gastric cancer subtypes was achieved with emphasis." (PMID 35664756, 2022). "However, in gastric cancer, ANXA10 plays a role in suppressing cancer." (PMID 35693827, 2022). "For example, a lower expression of genes that may play an important role in suppressing gastric cancer (GKN1, LIPF, ANXA10, MUC6, PSCA, and SNHG5) was found." (PMID 35625760, 2022).
bladder cancer (15 papers, 2011 to 2025). "We showed that down-regulation of ANXA10 caused up-regulation of S100A4 in the SW780 bladder cancer cell line." (PMID 21979422, 2011). "Similarly, ANXA10, a gene that encodes a member of the annexin family is reported for the first time to be correlated with bladder cancer." (PMID 21483740, 2011). "Several of the individual genes upregulated by Gardnerella exposures are involved in epithelial to mesenchymal transition (Cxcl5, Cxcr2, Tff1) or known to be elevated during squamous metaplasia or bladder cancer (Anxa10, Fosl1, Krt6a, Mmp10)." (PMID 35782131, 2022). "In bladder cancer, the downregulation of ANXA10 is also related to the aggressiveness of the cancer." (PMID 31052599, 2019). "In our study, down-regulation of ANXA10 in a bladder cancer cell line resulted in increased proliferation and migration." (PMID 21979422, 2011). "We showed that down-regulation of ANXA10 in a bladder cancer cell line (SW780) resulted in up-regulation of S100A4." (PMID 21979422, 2011). "Our study indicates an association between expression levels of ANXA10 and S100A4 in bladder cancer." (PMID 21979422, 2011). "We studied the phenotypic effects in a SW780 bladder cancer cell line, endogenously expressing ANXA10." (PMID 21979422, 2011). "For validation of the prognostic value of ANXA10 at the protein level, we immunostained a bladder cancer tissue microarray." (PMID 21979422, 2011). "We conclude that ANXA10 may be a clinical relevant marker for predicting outcome in both early and advanced stages of bladder cancer." (PMID 21979422, 2011). "Finally, we found that down-regulation of ANXA10 in a bladder cancer cell line induced increased proliferation and migration." (PMID 21979422, 2011). "Furthermore, we investigated the functional role of ANXA10 in bladder cancer cell lines by siRNA-mediated ANXA10 knockdown using wound healing, proliferation assays, and ingenuity pathway analysis (IPA)." (PMID 21979422, 2011). "Based on these findings, CRH, ANXA10, and IGF2 were considered bladder carcinoma markers, and were therefore detected in urine samples." (PMID 37569864, 2023). "The XPERT© Bladder Cancer Monitor is a test for detecting the five mRNA sequences (ABL1, CRH, IGF2, UPK1B, ANXA10) in urine." (PMID 35804953, 2022). "Based on the detection of five mRNA targets in urine (CRH, IGF2, UPK1B, ANXA10, and ABL1), Xpert Bladder Cancer (Xpert BC) is a recently developed detector for the detection of bladder cancer, which is non-invasive and highly economical." (PMID 33563292, 2021). "We also analyzed the possible role of ANXA-L (ANXA4, ANXA9, ANXA10, and ANXA11) in the regulation of luminal bladder cancer." (PMID 34484309, 2021). "The expression of ANXA1, ANXA2, ANXA3, ANXA5, ANXA6, ANXA8, and ANXA13 was closely related to basal-subtype bladder cancer, while the expression of ANXA4, ANXA9, ANXA10, and ANXA11 was closely related to luminal-subtype BC." (PMID 34484309, 2021). "Interestingly, we found that bladder cancer with high expression of ANXA1 also showed a squamous pattern, while bladder cancer with high expression of ANXA10 showed a papillary pattern." (PMID 34484309, 2021).
hepatocellular carcinoma (12 papers, 2011 to 2023). A malignant tumor that arises from hepatocytes. "On the contrary, annexin A10 was associated with a favorable prognosis for hepatocellular carcinoma." (PMID 35227227, 2022). "The expression of short isoform mRNA of annexin A10, previously mistaken as annexin A10, was associated with favorable prognosis in hepatocellular carcinoma." (PMID 35227227, 2022). "Studies have shown that ANXA10 was down-regulated in hepatocellular carcinoma and was associated with a poor prognosis." (PMID 30744186, 2019). "DLX6-AS1 inhibits ANXA10 expression through ubiquitination-mediated degradation to accelerate hepatocellular carcinoma development, which can be attributed to the regulation on miR-513c/Cul4A axis." (PMID 36660176, 2023). "While ANXA10 plays a diverse role in different tumours, in hepatocellular carcinoma, the overexpression of ANXA10 significantly promotes apoptosis." (PMID 36936694, 2023). "In former studies, overexpression of ANXA10 suppresses proliferation and promotes apoptosis of hepatoma." (PMID 36158697, 2022). "To date, ANXA10 has been reported as an independent prognostic factor in hepatocellular carcinoma, ovarian cancer, cholangiocarcinoma, and thyroid cancer." (PMID 33177783, 2020). "AnxA10 is already used as a biomarker for hepatocellular carcinoma (HCC) and is markedly downregulated during cancer progression." (PMID 29914106, 2018). "Furthermore, ANXA10 has been reported to be correlated with poor prognosis in both hepatocellular carcinoma and gastric carcinoma." (PMID 21979422, 2011). "Overexpression of ANXA10 could promote apoptosis of hepatocellular carcinoma cells." (PMID 39290334, 2022).
colorectal cancer (7 papers, 2011 to 2023). A primary or metastatic malignant neoplasm that affects the colon or rectum. "In neoplasms of other organs, especially colorectal cancer, ANXA10 is associated with CpG island methylation and BRAF mutation." (PMID 33177783, 2020). "Aberrant ANXA10 expression has been reported to be closely associated with adenocarcinomas of the gastric and pancreatobiliary system as well as colorectal carcinoma (CRC)." (PMID 28369074, 2017). "The ANXA10 expression was highly related to gastric phenotype in the serrated pathway to colorectal carcinoma and associated with poor prognosis in CRCs." (PMID 28369074, 2017). "ANXA10 has recently been identified as a marker with high specificity for the serrated histology of colorectal cancer." (PMID 30744186, 2019). "Increased expression of ANXA10 was closely related to a gastric phenotype in serrated pathway to colorectal carcinoma while the downregulation of ANXA10 was correlated with tumor progression in intestinal-type gastric carcinoma." (PMID 28369074, 2017).
lung carcinoma (6 papers, 2011 to 2025). "The knockdown of Cul4A is associated with the increased expression of ANXA10, a tumor suppressor protein, in lung cancer cells." (PMID 31052599, 2019). "The knockdown of Cul4A was associated with the upregulation of ANXA10, and the forced expression of Cul4A was associated with the downregulation of ANXA10 in lung cancer cells." (PMID 31052599, 2019). "Our study showed that the overexpression of Cul4A was associated with the downregulation of the tumor suppressor ANXA10 in lung cancer tissues and cells, which may provide another mechanism for the role of Cul4A in lung cancer invasion and metastasis." (PMID 31052599, 2019). "A previous report showed that ANXA10, regulated by Cullin 4A, modulates invasion and metastasis of lung cancer." (PMID 33177783, 2020). "Similar to the results observed with transient siRNA transfection, H460 and A549 lung cancer cells were stably transfected with Cul4A shRNA using retroviral transduction, which resulted in the knockdown of Cul4A, and showed increased ANXA10 protein levels." (PMID 31052599, 2019). "Our findings suggest that Cul4A is a prognostic marker in NSCLC patients, and Cul4A plays important roles in lung cancer invasion and metastasis through the regulation of the ANXA10 tumor suppressor." (PMID 31052599, 2019). "Protein degradation assay was used to evaluate the stability of ANXA10 protein in Cul4A knockdown and overexpressed H460 lung cancer cells." (PMID 31052599, 2019). "The expression of ANXA10 mRNA was further evaluated by RT-PCR in the Cul4A knockdown H460 and A549 lung cancer cells." (PMID 31052599, 2019). "Further experimentation revealed that Cul4A regulates ANXA10 through ubiquitination and protein degradation in lung cancer cells." (PMID 31052599, 2019). "In our previous unpublished study, the upregulation of ANXA10 was observed in Cul4A knockdown lung cancer cells." (PMID 31052599, 2019). "Further studies showed that the knockdown of Cul4A inhibited the invasion and metastasis of lung cancer cells, which was reversed by the further knockdown of ANXA10." (PMID 31052599, 2019). "Both cell migration and invasion were restored following the knockdown of ANXA10 in Cul4A knockdown H460 and A549 lung cancer stable cells." (PMID 31052599, 2019). "We observed an increase in the ANXA10 protein level in Cul4A knockdown lung cancer cells using western blotting." (PMID 31052599, 2019). "In conclusion, our results showed that Cul4A is important in lung cancer cell invasion and metastasis through the inhibition of ANXA10, a tumor suppressor." (PMID 31052599, 2019). "Cul4A also plays important roles in lung cancer invasion and metastasis partially through ubiquitin-mediated protein degradation of ANXA10 in lung cancer cells." (PMID 31052599, 2019). "An increased expression of ANXA10 was also observed in the Cul4A knockdown H460 and A549 cells compared to the empty virus transfected lung cancer cells." (PMID 31052599, 2019). "Down-regulation of ANXA10 has been reported in response to up-regulating of S100A4 in a lung cancer cell line." (PMID 21979422, 2011). "ANXA10 has been described to be down-regulated in response to up-regulation of S100A4 in a lung cancer cell line." (PMID 21979422, 2011). "First, ANXA10 has been reported to be down-regulated in response to up-regulation of S100A4 in a lung cancer cell line." (PMID 21979422, 2011). "Cul4A overexpression in the H460 lung cancer cells resulted in lowered protein levels of ANXA10." (PMID 31052599, 2019). "Notably, Cul4A regulated the degradation of ANXA10 through its interaction with ANXA10 and ubiquitination in lung cancer cells." (PMID 31052599, 2019). "Our results add ANXA10 to the repertoire of tumor suppressor proteins that are inhibited by Cul4A in cancer, and thus, it suggests Cul4A as a potential drug target for the development of novel therapy for lung cancer in the future." (PMID 31052599, 2019).
lung carcinoma (continued). "Additionally, the upregulation of S100A4, which is considered a mediator of metastasis, has been reported to downregulate ANXA10 in a lung cancer cell line." (PMID 31052599, 2019). "In our study, the knockdown of ANXA10 increases lung cancer cells migration and invasion." (PMID 31052599, 2019). "Since other annexin proteins, including ANXA1, A2, and A7 have been observed to be regulated by ubiquitination, we thus postulated that ANXA10 may also be regulated by Cul4A through ubiquitination in lung cancer cells." (PMID 31052599, 2019). "The role of ANXA10 as a tumor and metastasis suppressor in lung cancer cells was further confirmed." (PMID 31052599, 2019). "We hypothesized that Cul4A mediated degradation of ANXA10 was one of the key mechanisms in lung cancer invasion and metastasis." (PMID 31052599, 2019). "Additionally, up-regulation of S100A4, which is considered a mediator of metastasis, has been reported to down-regulate ANXA10 in a lung cancer cell line." (PMID 21979422, 2011). "Remarkably, no obvious change in the ANXA10 mRNA levels was observed in the Cul4A shRNA transfected groups of lung cancer cells compared to the cells transfected with the empty vector." (PMID 31052599, 2019).
cholangiocarcinoma (5 papers, 2020 to 2023). A carcinoma that arises from the intrahepatic biliary tree (intrahepatic cholangiocarcinoma) or from the junction, or adjacent to the junction, of the right and left hepatic ducts (hilar cholangiocarcinoma). "ANXA10 has been recognized as a valuable diagnostic tool in differentiating liver PDAC metastases from cholangiocarcinoma or other malignancies, with a sensitivity and specificity of 83% and 95%, respectively." (PMID 37760554, 2023). "We explored the association of annexin A10 expression with the overall survival (OS) of patients who underwent curative surgery for cholangiocarcinoma." (PMID 35227227, 2022). "Annexin A10 was not only associated with the prognosis of cholangiocarcinoma, but also other gastrointestinal and hepatobiliary cancers." (PMID 35227227, 2022). "Similar to our findings for cholangiocarcinoma, annexin A10 was associated with a poor prognosis for small bowel adenocarcinoma in another study." (PMID 35227227, 2022). "Patients with grade 4 cholangiocarcinoma exhibited significantly poorer OS than patients with grade 1–3 cholangiocarcinoma (p = 0.017) and similar OS compared to patients with annexin A10 positive cholangiocarcinoma (p = 0.209)." (PMID 35227227, 2022). "A previous study suggested the use of annexin A10 as a prognostic marker for cholangiocarcinoma but discovered that it had prognostic value only for perihilar and distal cholangiocarcinoma." (PMID 35227227, 2022). "All patients with grade 4 cholangiocarcinoma (n = 15) tested negative for annexin A10 staining; thus, the association of annexin A10 staining results with prognosis in these patients could not be analyzed." (PMID 35227227, 2022).
oral squamous cell carcinoma (4 papers, 2012 to 2024). "Moreover, ANXA10 was linked to the EMT processes in oral squamous cell carcinoma, facilitating the migration of melanoma cancer, and stimulating the EMT during liver cancer metastasis." (PMID 39682235, 2024). "ANXA10 belongs to the annexin family, and is over-expressed in oral squamous cell carcinoma-derived cell lines." (PMID 24962627, 2014). "In this study, we investigated the involvement of ANXA10 in oral squamous cell carcinoma (OSCC)." (PMID 23029062, 2012).